KIF3A (kinesin family member 3A)
Diseases named in the same sentence as KIF3A in open-access papers (continued):
Sharing a sentence is not in itself a finding about the gene and the disease.
rhinitis (2 papers, 2017 to 2026). An inflammation of the mucous membrane lining the nose, usually associated with nasal discharge. "Some allelic variants of genes were found to be associated with conjunctivitis (FLG), rhinitis (KIF3A), bronchial asthma (IL5RA) comorbidities and high IgE levels (ADAM33)." (PMID 42039188, 2026). "Interestingly, seven KIF3A SNPs were actually reported to be associated with rhinitis in one study that was not incorporated to the databases used in this study, thus supporting the reliability of the prediction method." (PMID 28598986, 2017).
type 2 diabetes (2 papers, 2021 to 2025). "According to the literature study, some genes that are associated with developmental dyslexia, such as ROBO1, DCDC2, DYX1C1, and KIA0319, and some genes that are associated with type 2 diabetes CTNNB1, TCF7L2, and KIF3A had shown some connections with each other." (PMID 34674647, 2021). "As it was mentioned before, KIF3A is involved in the regulation of phosphorylation and stabilization of β-catenin, which interacts with TCF family proteins, which are associated with the increased risk of developing type 2 diabetes." (PMID 34674647, 2021). "In addition to this, KIF3A, which is a kinesin motor protein and an essential subunit for the transportation along microtubules in cilium and cytoplasm in the neurons, is also a critical gene in the development of type 2 diabetes." (PMID 34674647, 2021).
amyotrophic lateral sclerosis (1 paper, 2011). Amyotrophic lateral sclerosis (ALS) is a neurodegenerative disease characterized by progressive muscular paralysis reflecting degeneration of motor neurons in the primary motor cortex, corticospinal tracts, brainstem and spinal cord. "Kif3a is a kinesin gene involved in moving axon cargo and has been implicated in amyotrophic lateral sclerosis, a disease involving degeneration of motor neurons." (PMID 21410935, 2011).
Anxiety (1 paper, 2025). Intense feelings of nervousness, tension, or panic often arise in response to interpersonal stresses. "By contrast, downregulation of Ift20 or Kif3a did not affect performance in the open-field test (OFT) and the light/dark test (LDT), indicating that exploratory-like and anxiety-like behaviors are unaffected." (PMID 39984747, 2025).
childhood asthma (1 paper, 2011). "Our study demonstrates that KIF3A, a member of the kinesin superfamily of microtubule associated motors that are important in the transport of protein complexes within cilia, is a novel candidate gene for childhood asthma." (PMID 21912604, 2011).
colorectal cancer (1 paper, 2019). A primary or metastatic malignant neoplasm that affects the colon or rectum.
dwarfism (1 paper, 2014). "The authors found that a conditional knock out of the IFT protein Kif3a in the chondrocytes of mice embryos, resulting in a lack of primary chondrocyte cilia, led to a disrupted columnar orientation in the growth plate and post-natal dwarfism." (PMID 25335082, 2014).
frontonasal dysplasia (1 paper, 2024). A group of rare bone development disorders characterized by an array of abnormalities affecting the eyes, forehead, and nose, and linked to midfacial dysraphia. "Another relative gene is Kif3a, with mice lacking neural crest Kif3a expression featuring a wider frontonasal process and facial clefts, similar to the phenotype of human frontonasal dysplasia." (PMID 38673496, 2024).
Hyperkeratosis (1 paper, 2020). Hyperkeratosis is a histopathological term defining a thickened stratum corneum and may be present in many different skin conditions, with many possible overlaps. "Parakeratosis, hyperkeratosis, and hypergranulosis were focally present in Kif3aK14∆/∆ mice with these findings being rare in Kif3a+/+ mice." (PMID 32796837, 2020).
Hypertelorism (1 paper, 2025). Interpupillary distance more than 2 SD above the mean (alternatively, the appearance of an increased interpupillary distance or widely spaced eyes). "Among them, mice with a deficiency for Fgfr1, Fgfr2, Kif3a, Kras, Ptch1, Rreb1, Sos1, and Tfap2a show excessive proliferation during midfacial development, resulting in hypertelorism, suggesting that mimics of miR-383-3p and miR-6951-3p activate cell proliferation through suppression of these genes." (PMID 40787625, 2025).
infertile (1 paper, 2013). "KIF3A knockout males are infertile due to severe morphological defects of the sperm head and flagellum, indicating that KIF3A is essential for sperm head and tail formation." (PMID 24339785, 2013).
injury (1 paper, 2024). Damage inflicted on the body as the direct or indirect result of an external force, with or without disruption of structural continuity. "Our previous research has shown that KIF3A is involved in the regulation of sodium channel Nav1.6 membrane trafficking in DRG neurons, which contributes to the pathological pain induced by nerve injury or the chemotherapeutic drug oxaliplatin." (PMID 38475827, 2024).
invasive breast carcinoma (1 paper, 2025). A carcinoma that infiltrates the breast parenchyma. "It has been hypothesized that the RFX1 binding site is also present in the promoter of the human kinesin family member 3A gene, and that inhibition of this transcriptional process could be beneficial in suppressing invasive breast cancer." (PMID 41425715, 2025).
Microglossia (1 paper, 2023). Decreased length and width of the tongue. "For example, mesenchymal-specific deletion of the TGFBR2 gene in TGFβ signaling and loss of KiF3a and intraflagellar proteins in Shh signaling lead to microglossia and aglossia, respectively." (PMID 37680190, 2023).
myocardial infarction (1 paper, 2011). Gross necrosis of the myocardium, as a result of interruption of the blood supply to the area, as in coronary thrombosis. "Similar to the PAR of this KIF3A variant, the PAR for myocardial infarction was 21% in individuals with the previously reported rs10757278 variant located in adjacent CDKN2A and CDKN2B genes." (PMID 21912604, 2011).
neuritis (1 paper, 2023). A neuropathy arising from inflammation of one or more nerves. "In TTLL1 mutant mice, the targeting of KIF1A, a subfamily of kinesin-3 in neuritis, was impaired, but the distribution of KIF3A (kinesin-2) and KIF5 (kinesin-1) was not altered." (PMID 37321451, 2023).
neuroblastoma (1 paper, 2021). Neuroblastoma (NB) is the most common solid, extracranial childhood tumor. "In IMR32 neuroblastoma cells, DUSP26 co-immunoprecipitated with N-cadherin, β-catenin and the KIF3 motor complex via the KIF3a subunit." (PMID 33466673, 2021).
prostate tumor (1 paper, 2023). "Other kinesin superfamily proteins, such as KIF2C or KIF3A are associated with prostate tumor progression." (PMID 34593983, 2023).
silicosis (1 paper, 2020). Silicosis is a respiratory disease caused by breathing in (inhaling) silica dust. "Our findings indicate that primary cilia are markedly altered during silicosis and loss of KIF3A may promote myofibroblast differentiation." (PMID 32042332, 2020). "The purpose of this study was to determine the effects of Kinesin family member 3A (KIF3A) on primary cilia and myofibroblast differentiation during silicosis by regulating Sonic hedgehog (SHH) signalling." (PMID 32042332, 2020). "The levels of KIF3A and IFT88 were increased in rats exposed to silica for 4 weeks and decreased in the 24-week silicosis group compared with their control groups." (PMID 32042332, 2020).
triple-negative breast carcinoma (1 paper, 2022). An invasive breast carcinoma which is negative for expression of estrogen receptor (ER), progesterone receptor (PR), and human epidermal growth factor receptor 2 (HER2). "In addition, KIF3A knockdown impairs the proliferation of triple-negative breast cancer cells by suppressing the Rb-E2F signaling pathway." (PMID 35821021, 2022).
tumor (22 papers, 2013 to 2025). "The results showed that the EVs-miR-139-5p-inhibitor led to increased tumor volume and weight, while further sh-KIF3A caused opposite trends." (PMID 35821021, 2022). "Detailedly, lyn 1 metastasis originated from a distinct primary tumor, and carried missense mutations in a putative driver gene (i.e., KIF3A)." (PMID 34249677, 2021). "Taken together, these results indicate that loss of KIF3A aggravates tumour growth and increases tumour cell migratory behavior." (PMID 27596264, 2016). "Taken together, overexpression of POPX2 in the cells could contribute to tumor invasion through loss of adhesion, polarity and increased cell motility via KIF3A-mediated cargo transport, MAPK pathway activation, and modulation of the microtubules." (PMID 33037179, 2020). "For validation in vivo, we injected T24 cells subcutaneously into nude mice to establish a subcutaneous transplantation tumor model, and then injected EVs-miR-139-5p-inhibitor or combined with sh-KIF3A." (PMID 35821021, 2022). "Given the anti-tumor effects of KIF3A knockdown in vitro, we also investigated the role of primary cilia in AT/RT biology in vivo." (PMID 36127323, 2022). "Tumour suppression activity was validated in vitro, and the KIF3A-mediated ERK1/2/β-catenin/MMP7 signalling pathway was demonstrated to mediate the anti-tumour function, at least in part." (PMID 28423710, 2017). "Next, to demonstrate the tumourigenicity of KIF3A-depleted cells, we implanted the cells into nude mice through subcutaneous injection, and measured the tumour volume." (PMID 27596264, 2016). "Despite its observed roles in the previous tumor types, little is known about the roles of KIF3A in GBM." (PMID 26760767, 2016). "It is likely that KIF3A functions to limit the number of cancer cells acquiring stemness within the tumour mass through its inhibitory role in autocrine Wnt/β-catenin signalling." (PMID 27596264, 2016). "Taken together, our results indicate that KIF3A plays a role as a tumour suppressor, inhibiting Wnt/β-catenin signalling in NSCLCs." (PMID 27596264, 2016). "Immunohistochemically stained samples were categorized into three groups (0, 1, and 2) according to the estimated KIF3A expression levels in the tumour cells compared with the expression in normal bronchial epithelial cells." (PMID 27596264, 2016). "In our current study, we reveal a tumour suppressor role for KIF3A as an inhibitor of the Wnt/β-catenin pathway in NSCLC cells." (PMID 27596264, 2016). "In contrast, SW900 cells depleted of KIF3A formed a larger initial tumour mass, and the tumour volume doubling time was less than 3 weeks." (PMID 27596264, 2016). "Intriguingly, in mutants driven by oncogenic Smo, simultaneous blocking of cilia formation by knocking out Kif3a or Ift88, resulted in impaired GliA formation and inhibition of tumorigenesis, suggesting that in this model, tumor formation is cilia-dependent." (PMID 23628112, 2013). "In addition, miR-139-5p expression and p-p21/p21 ratio were decreased and KIF3A expression was increased in the tumor tissues of EVs-miR-139-5p inhibitor-treated mice." (PMID 35821021, 2022). "Knockdown of KIF3A resulted in a significant reduction of tumor-promoting properties." (PMID 36127323, 2022). "Interestingly, KIF3A expression pattern of primary tumours was mostly sustained after post-surgical tumour recurrence." (PMID 27596264, 2016). "Our results indicate that KIF3A is a class of tumour suppressor in NSCLC." (PMID 27596264, 2016).
tumor (continued). "Moreover, KIF3A is a potential tumour suppressor in NSCLC, suppressing both autocrine Wnt/β-catenin signalling and stem cell-like properties." (PMID 27596264, 2016). "KIF3A, a component of the kinesin-2 motor, is necessary for the progression of diverse tumor types." (PMID 26760767, 2016). "Next, we compared KIF3A expression between primary tumours and recurred tumours." (PMID 27596264, 2016). "Importantly, we observed a decrease in cyclin D1-positive cell numbers in tumour samples expressing higher levels of KIF3A." (PMID 27596264, 2016). "To elucidate the biological mechanism that could be responsible for the anti-tumor effects following disruption of primary ciliogenesis, we conducted comprehensive analysis of the transcriptome and the proteome following transient KIF3A knockdown in BT-12 and CHLA-266 cells." (PMID 36127323, 2022). "The results confirmed that knockdown of KIF3A and IFT88 significantly inhibited ciliogenesis in tumor tissues." (PMID 39389955, 2024). "Inhibiting expression of KIF3a, PCM1, ARL13B, or IFT88, all proteins required for ciliogenesis, can sensitize patient-derived tumor cells to TMZ in vitro and in vivo." (PMID 38630257, 2023). "In recent years, several studies have identified the role of KIFs (KIF3A and KIF3B) in human cancers, confirming the effect of kinesin on the proliferation or invasion of tumor cells." (PMID 33150178, 2020). "However, the expression of a constitutively-active human GLI2, in concomitance with the loss of Kif3a-induced cilia resorption, did not protect against tumor formation, but instead drove faster neoplastic growth, with a hyperactivation of Hedgehog signaling (panel “HYPER ON”)." (PMID 30884815, 2019). "Notwithstanding the potential extraciliary functions for KIF3A and IFT88, our findings suggest that GBM cilia play an important role in tumor growth and therapeutic resistance." (PMID 30410731, 2018). "To validate the potential tumour suppressor function of KIF3A in NSCLC, we first examined the expression of KIF3A and β-catenin in 233 tumour tissue samples from 110 NSCLC patients who had multiple synchronous or metachronous tumours." (PMID 27596264, 2016). "Therefore, our findings so far suggest that KIF3A might play a role as a tumour suppressor." (PMID 27596264, 2016). "In some tumor types, SHH-driven tumorigenesis is sensitive to the disruption of KIF3A, a subunit of the kinesin-2 motor whose anterograde function is required for ciliogenesis." (PMID 26760767, 2016). "Protein expression of KIF3A was significantly lower in NSCLC compared to adjacent normal tissue and lower in LUAD than in LUSC tumours; low expression was correlated with higher TNM stage in LUAD and lymph node metastasis in LUSC, revealing KIF3A as a putative prognostic factor in NSCLC." (PMID 40002279, 2025). "Besides, the depletion of KIF3A and IFT88, genes required for ciliogenesis, significantly inhibited tumor proliferation and metastasis in vitro and in vivo." (PMID 39389955, 2024). "In addition, multiple studies have found that disrupting key ciliary regulators such as KIF3A and ARL13B on GBM cells derived from various subtypes somewhat consistently prolonged survival in tumor-bearing mice." (PMID 38630257, 2023). "However, suppressing cilia formation in other GBM cell lines, by disrupting critical ciliogenesis genes such as KIF3A or IFT88, had variable effects on tumor growth in vitro and in vivo." (PMID 30410731, 2018). "Therefore, compared to L0 and S2 cells, disruption of KIF3A in S3 cells did not noticeably alter the growth patterns of the tumor cells, in vitro or in vivo." (PMID 26760767, 2016).
cancer (15 papers, 2009 to 2025). A tumor composed of atypical neoplastic, often pleomorphic cells that invade other tissues. "Other genes from this list are linked to various types of cancer (Pnck, Calu, Vav2, Kif3a, Adgrf5, N4bp2l2)." (PMID 32467583, 2020). "Genes such as TPD52, HOXB1, and KIF3A have been implicated in other cancer types and are connected with MCC-associated signaling." (PMID 24634783, 2014). "This suggests that KIF3A loss provides a certain selective advantage for the survival of cancer." (PMID 27596264, 2016). "In prostate cancer, KIF3A silencing enhanced cancer migration and invasion through Wnt/β-catenin signaling." (PMID 36188577, 2022). "KIF3A knockdown in triple-negative breast cancer cell lines significantly attenuated in vitro cancer migration and invasion and in vivo metastasis." (PMID 36188577, 2022). "We also found GIST to highly express four genes (KIF3A, IFT52, IFT88, and IFT172), which are associated with PC function in several cancers." (PMID 27793025, 2016). "In addition to these genes, there were other genes that were of interest and associated with cancer development or progression including dimethylarginine dimethylaminohydrolase 1 (DDAH1), kinesin family member 3A (KIF3A), and MUC1 which are all upregulated in the poor prognosis samples." (PMID 24634783, 2014). "Kif3A that promote PCa, NPPB, a potential oncogene, and ILF‐3, a cancer stem cell upstream regulator, are downregulated by 433‐3β treatment." (PMID 40007440, 2025). "The upregulation of KIF3A activates this pathway by increasing DVL2 phosphorylation and β-catenin levels, promoting MMP9 and HEF1 expression and inducing cancer invasion and migration." (PMID 36188577, 2022). "We next investigated if the expression level of KIF3A, KIF13A, and KIF9 correlates with cancer progression." (PMID 35122963, 2022). "According to our search on the Pathology Atlas, Kif3a gene alterations are not considered prognostic markers for different cancer types." (PMID 35122963, 2022). "The data presented here suggest that KIF5B is implicated in several pathwaysinvolving lysosomes and that its highly expressed in all cancer cell lines tested,as compared to other N-Kinesins including KIF5A/KIF5C (Kinesin 1 family), KIF3A(Kinesin 2 family) and KIF1A (Kinesin 3 family)." (PMID 19242560, 2009). "Silencing of KIF3A demonstrated that the epithelial to mesenchymal transition was strongly suppressed by the downregulation of a transcription factor, ZEB1, and vimentin, as opposed to the upregulation of the epithelial marker E-cadherin, thereby inhibiting cancer metastasis." (PMID 36188577, 2022).
infection (3 papers, 2009 to 2018). The state of being infected such as from the introduction of a foreign agent such as serum, vaccine, antigenic substance or organism. "Other Epo responsive genes did appear to respond to infection: Eif1a (Eukaryotic translation initiation factor) and Kif3a (kinesin family member 3A) were up regulated in all three mouse strains at day 7 and 9 respectively." (PMID 19365556, 2009). "Notably, AdV-Kif3a restored primary cilia and canonical HH signaling at a multiplicity of infection (MOI = 10) that resulted in KIF3A expression below endogenous KIF3A levels in WT MEFs." (PMID 30148884, 2018).
inflammation (1 paper, 2025). Aberrant reaction of the microcirculation characterized by movement of fluid and leukocytes from the blood into extravascular tissues. "Thus, we concluded that MC down‐regulates LPS‐induced apoptosis and autophagy‐related protein expression and increases Kif3a expression to attenuate LPS‐induced airway inflammation in 16HBE cells." (PMID 39949885, 2025).
psychiatric disorder (1 paper, 2025). A disorder characterized by behavioral and/or psychological abnormalities, often accompanied by physical symptoms. "As a candidate for a crucial Kifs gene that is likely related to microglia polarization, we selected psychiatric disorder-related KIFs (KIF3A, KIF17, KIF1A, KIF1B, and KIF13A)." (PMID 39885501, 2025). "KIF3A and KIF17 that specifically transport NMDAR subunit 2 A and 2B in neurons, respectively, are involved in the pathogenesis of psychiatric disorders." (PMID 39885501, 2025).